TRMT5 (tRNA methyltransferase 5)
Description:
Involved in mitochondrial tRNA methylation. Specifically methylates the N1 position of guanosine-37 in various tRNAs. Methylation is not dependent on the nature of the nucleoside 5' of the target nucleoside. This is the first step in the biosynthesis of wybutosine (yW), a modified base adjacent to the anticodon of tRNAs and required for accurate decoding.
Synonyms: KIAA1393; TRM5; COXPD26; PNSED
Tractability: PROTAC: ubiquitination databases record sites on it; its protein half-life has been measured.
Gene: Protein-coding gene on chromosome 14 (60,971,441 to 60,981,170, reverse strand). Ensembl gene ENSG00000126814.
Subcellular location: Mitochondrion matrix; Nucleus; Cytoplasm
Subcellular location (Human Protein Atlas): Nucleoli; Nucleoplasm
Pathways (Reactome):
Metabolism of RNA: Synthesis of wybutosine at G37 of tRNA(Phe)
Gene Ontology:
Molecular function: tRNA (guanine(37)-N1)-methyltransferase activity
Biological process: mitochondrial tRNA methylation; tRNA methylation
Cellular component: mitochondrial matrix; mitochondrion; cytoplasm; nucleus
Genetic constraint (gnomAD): Loss-of-function variants: 33 observed, 45.54 expected, observed/expected ratio (o/e) 0.72, 90% interval 0.55 to 0.97. The upper end of that interval is the gene's LOEUF score, 0.97, which puts it in group 4 of 6, group 1 being the genes least tolerant of losing a copy. Missense variants: 568 observed, 622.49 expected, observed/expected ratio (o/e) 0.91, 90% interval 0.85 to 0.98. Synonymous variants: 198 observed, 220.94 expected, observed/expected ratio (o/e) 0.9, 90% interval 0.8 to 1.01.
Gene-disease validity (ClinGen):
ClinGen rates the evidence that TRMT5 causes each of these diseases.
mitochondrial disease (autosomal recessive): Definitive.
Homologues: Orthologues: chimpanzee TRMT5 (99% identical), macaque TRMT5 (94% identical), pig TRMT5 (85% identical), dog TRMT5 (82% identical), guinea pig TRMT5 (80% identical), rabbit TRMT5 (76% identical), mouse Trmt5 (75% identical), rat Trmt5 (75% identical), tropical clawed frog trmt5 (55% identical), zebrafish trmt5 (50% identical), Drosophila melanogaster CG32281 (38% identical), Caenorhabditis elegans C53A5.17 (30% identical). Paralogues in human: TYW2 (15% identical), TYW3 (6% identical).
Diseases named in the same sentence as TRMT5 in open-access papers:
TRMT5 is named in the same sentence as 16 diseases in open-access papers, as found by Europe PMC text mining. Sharing a sentence is not in itself a finding about the gene and the disease. The quoted sentences say what the papers report.
glioblastoma (1 paper, 2026). The most malignant astrocytic tumor (WHO grade IV). "Patients with GVs in SDHA (n = 3) or TRMT5 (n = 4) were exclusively affected by glioblastoma, IDH-wildtype." (PMID 41546701, 2026).
hepatocellular carcinoma (1 paper, 2024). A malignant tumor that arises from hepatocytes. "Although the regulatory mechanism is not clear, it is reported that TRMT5 was increased in hepatocellular carcinoma (HCC) and correlated with poor prognoses." (PMID 39456272, 2024).
lactic acidosis (1 paper, 2020). Metabolic acidosis characterized by the accumulation of lactate in the body. "Similarly, mutations of the tRNA methyltransferase 5 (TRMT5), which methylates G37 within the anticodon loop of specific tRNAs, lead to numerous pathologies including mitochondrial myopathy and lactic acidosis." (PMID 32217072, 2020).
liver cancer (1 paper, 2024). An epithelial or non-epithelial malignant neoplasm that arises from the liver. "In addition, there are other mt-tRNA methyltransferases, including TRMT5 (an m1G methyltransferase) and TRMT10C (an m1A methyltransferase), that have been reported to be associated with liver cancer progression." (PMID 39019857, 2024).
neuropathy (1 paper, 2021). A disorder affecting the nervous system that manifests with pain, tingling, numbness, and/or muscle weakness. "The 22nd ranked gene TRMT5 was found to affect motor intolerance and neuropathy, leading to muscle weakness, growth retardation, and spastic paraparesis." (PMID 34492068, 2021).
Stroke (1 paper, 2022). Sudden impairment of blood flow to a part of the brain due to occlusion or rupture of an artery to the brain. "In the TRMT5 gene, the variant with the strongest individual association, rs115400838 (p.Ser185Cys), was associated with multiple stroke phenotypes, e.g., “stroke, excluding subarachnoid hemorrhage” (p=1.90×10−4)." (PMID 36419110, 2022).
TRMT5 also shares sentences with these, for which no sentence is quoted: brain disorder (1 paper); cancer (1); developmental delay (1); Failure to thrive (1); glioma (1); hepatopulmonary syndrome (1); hereditary spastic paraparesis (1); Mitochondrial myopathy (1); Spastic paraparesis (1); subarachnoid hemorrhage (1).